PINK1 (PTEN induced kinase 1)
Diseases named in the same sentence as PINK1 in open-access papers (continued):
Sharing a sentence is not in itself a finding about the gene and the disease.
cancer (continued). "With regards to mitophagy, its dysregulation in the pathogenesis of other cancers has previously been demonstrated and the Pink1-parkin mitophagy pathway is known to be altered in COPD." (PMID 30526542, 2018). "While much current evidence points to PINK1 as a tumor promoter and mediator of chemo resistance, PINK1 possesses a dual role in cancer biology, with context dependent pro- and antitumorigenic properties." (PMID 30595797, 2018). "In this review, we highlight that PARKIN, PINK1, and DJ-1 should be regarded as having an important role in Cancer Biology." (PMID 30274236, 2018). "According to their data, the combined expression of BUB1B and PINK1 was the best predictor of OS among carcinomas." (PMID 29520253, 2018). "PINK1 deletion reduces, and PINK1 overexpression restores, cancer cell proliferation, colony formation, and invasiveness, indicating that PINK1 promotes cell cycle progression and acts as an oncogene." (PMID 28060722, 2017). "Consistently, we found G-TPP mediated activation of PINK1/Parkin not only in cancer cells (HeLa) but also in primary skin fibroblasts and thereof converted iNeurons." (PMID 29290944, 2017). "In this study, we have carefully validated the response of cells upon treatment with G-TPP and found bona fide PINK1/Parkin mitoQC induction not only in cancer cells but also in primary human skin fibroblasts and induced neurons." (PMID 29290944, 2017). "Genetic studies provide additional understanding, since many familial PD genes have been associated with cancer, such as parkin (PARK2), PINK1 (PARK6), DJ-1 (PARK7), and LRRK2 (PARK8)." (PMID 27375474, 2016). "In a recent study we focused on the function of PINK1 in cancer cell biology, and discovered a novel function for PINK1 as a positive regulator of cell cycle progression that can promote cancer-associated phenotypes." (PMID 26973853, 2016). "PINK1 has been previously highlighted as a potential target for cancer therapy and been shown to sensitize cancer cells to DNA damaging agents and chemotherapeutic drugs." (PMID 26973853, 2016). "The PINK1 and LRRK2 somatic mutations identified in cancer were all heterozygous and their pathological effect remains to be determined." (PMID 21203498, 2010). "Targeting mitophagy-related genes such as PINK1 could enhance cancer cell sensitivity to treatment by disrupting mitochondrial clearance, leading to the accumulation of dysfunctional mitochondria, increased oxidative stress, and, ultimately, cell death." (PMID 40565152, 2025). "However, under specific stress conditions such as hypoxia or chemotherapy, the PINK1/Parkin signaling pathway can become reactivated in tumors, mitigating oxidative damage and promoting cancer cell survival." (PMID 40750884, 2025). "Additionally, PINK1 has been associated with glycolysis regulation and modulation of PI3K signaling, promoting cancer cell survival and proliferation." (PMID 40243539, 2025). "In addition, PINK1 insufficiency sensitizes tumors to mitochondria-centric combination therapies, including Mdivi-1 and indomethacin, potentiating the translational opportunities of RNA modification-mediated regulation of PINK1 to cancer treatment." (PMID 41373022, 2025). "For example, some studies demonstrate that PINK1 depletion in the non-small cell lung cancer (NSCLC) A549 cell line via shRNA reduced cancer cell proliferation, increased cell death, decreased ATP production, inhibited mitophagy, and increased ROS levels and caspase-9-dependent apoptosis." (PMID 40565152, 2025). "Recent evidence highlights critical interactions between the PI3K/AKT/mTOR pathway and PINK1, suggesting their crosstalk significantly impacts cancer progression, therapeutic resistance, and metabolic plasticity, especially under stress conditions such as metastatic dissemination to the brain." (PMID 40243539, 2025). "Another study also highlighted PINK1’s diverse role in cancer biology." (PMID 39859167, 2025).
cancer (continued). "PINK1 can initiate many defensive mechanisms to restore the normal mitochondrial functions and prevent oxidative stress which is essential for prolonging the survival of cancer cells." (PMID 39921807, 2025). "Additionally, while the role of PINK1 in cancer remains controversial, its possible dual function as a kinase dependent on the tumor subtype is consistent with the existing literature." (PMID 40565152, 2025). "Furthermore, we analyzed the relationship between the expression of the mitophagy‐related proteins Parkin and PINK1 and ferroptosis sensitivity in 207 cancer cell lines from different cancer types." (PMID 39679775, 2025). "Moreover, inhibition of PINK1/parkin- or ras-related protein Rab-9A (Rab9a)-mediated mitophagy has been shown to radiosensitize cancer cells." (PMID 40943612, 2025). "One factor that may play a protective role in both PD and cancer is the serine–threonine mitochondrial protein kinase PINK1." (PMID 38612708, 2024). "Furthermore, the implications of FBW7β in neurological disorders and the potential therapeutic significance of PINK1 in cancer highlight the broader implications of this research." (PMID 38508312, 2024). "Moreover, it has been observed that PINK1/Parkin-mediated mitophagy inhibition enhances the efficacy of betulinic acid analogue in multidrug-resistant cancers." (PMID 38514650, 2024). "PINK1 and Parkin are encoded by the Parkinson disease protein 6 (PARK6) and Parkinson disease protein 2 (PARK2) locus, respectively, which are frequently mutant in human cancers." (PMID 38262996, 2024). "Previous studies suggest that cancer mitophagy is primarily controlled by the PINK1/Parkin pathway." (PMID 38164280, 2024). "Recently, increasing attention has been drawn toward PINK1 in several diseases, including cancer." (PMID 37047483, 2023). "Although the role of PINK1 across cancers remains unclear, previous studies indicated that PINK1 influenced the prognosis of patients in some specific cancers." (PMID 37047483, 2023). "Previous research has shown that PINK1 is a downstream target of FOXO3a in cancers." (PMID 36823640, 2023). "This is confirmed by the analysis of PINK1 expression in the Human Protein Atlas, which states that PINK1 may be either beneficial or detrimental depending on the type of cancer." (PMID 36830954, 2023). "Given previous findings that the PINK1 gene is initially identified as an up-regulated target of PTEN in cancer cells, we hypothesized that PINK1 could interact with and regulate PTEN to form a loop." (PMID 37940999, 2023). "Moreover, various studies have reported PINK1’s critical role in cancer cell survival and resistance to chemotherapy, therefore indicating it as a potential therapeutic target for tumor treatment." (PMID 37940999, 2023). "Recently, PINK1 has been shown to affect cancer-related processes through mitophagy." (PMID 36823640, 2023). "Thus, the PINK1 signaling system has been shown to control several processes key to cancer cell biology, especially in mitochondrial homeostasis and dynamics, including bioenergetics, mitophagy, fission and fusion." (PMID 37047483, 2023). "At the same time, PINK1, as a cell cycle regulator, has the characteristics of promoting tumours and can significantly promote cell proliferation, colony formation, invasion and other cancer-related phenotypes." (PMID 36823640, 2023). "Further studies on PINK1 and its function in tumor biology are urgently needed to better understand disease mechanisms and to determine the therapeutic effect of PINK1 inhibition in cancer." (PMID 36830954, 2023). "Pink1 (aka BRPK and PARK6) is a 63 kDa mitochondrial serine/threonine-protein kinase encoded by the PINK1 gene that was first identified in 2001 as a target of phosphatase and tensin homolog (PTEN) in cancer cells." (PMID 35682755, 2022).
cancer (continued). "PINK1/Parkin has tumor suppressive activity and is frequently deleted in several types of cancers such as breast, ovarian, bladder, etc. confirming that the loss of function of PINK1/Parkin can lead to the inhibition of mitophagy and in turn promote tumorigenesis in various types of tumors." (PMID 36365094, 2022). "The use of cancer cell lines recombinantly overexpressing PINK1 has been called into doubt since some results obtained in immortalized cells and fibroblasts could not be reproduced in iPSC-derived neurons." (PMID 35203326, 2022). "PINK1 was initially identified as a downstream effector of phosphatase and tensin homolog (PTEN), a tumor suppressor that is frequently mutated in various types of human cancers." (PMID 35874823, 2022). "It have shown that PINK1‐mediated mitophagy provided cancer cells with resistance to chemotherapy and that inhibition of PINK1 by RNA interference could make cells more sensitive to conventional chemotherapy." (PMID 36200262, 2022). "To demonstrate whether MUC1 promoted cancer cell progression via Pink1, we performed a cell viability assay and mammosphere formation assay after silencing Pink1 in both MDA-MB-468 and BT549 cell lines." (PMID 36289190, 2022). "To further determine whether MUC1 promoted mitophagy through the Pink1-Parkin pathway, we detected Parkin expression in all three cancer cell lines, and HEK293T cells served as a positive control." (PMID 36289190, 2022). "In addition, the downregulation of PINK1 inhibits the proliferation, colony forming ability, and migration of cancer cells and increases the sensitivity of tumor cells to stressors." (PMID 34751247, 2021). "Although mitophagy may exhibit a dual role in tumorigenesis in general, the mitophagy mediated by the PINK1–Parkin pathway exerts tumor suppression in a variety of cancer types." (PMID 34361072, 2021). "PINK1 has an important pathophysiological function, so it could be a promising drug target in diseases such as neurodegeneration, aging, and cancer." (PMID 33912571, 2021). "Interestingly, YQ456 disrupted mitochondrial autophagy to induce cancer cell death by inhibiting Rab7‐meditated lysosomal degradation, as evidenced by the decline of PINK1/Parkin pathway, decreased LC3‐II/LC3‐I ratio, and elevated P62 expression." (PMID 33634965, 2021). "However, much of the PINK1/parkin mitophagy knowledge is derived from cancer cell lines treated with bulk uncoupling agents." (PMID 34688664, 2021). "Furthermore, specific genes are mutated or altered during the progression of cancer and AD such as α-synuclein, PTEN and PINK1." (PMID 34359949, 2021). "The upregulation of STOML2 could favor cyto-protective mitophagy via stabilizing PINK1 to facilitate cancer cell migration and invasion, relieve cellular stress, and regulate the sensitivity of HCC cells to lenvatinib." (PMID 33446239, 2021). "Thus, impaired mitophagy situations underlie the pathogenesis of a number of chronic diseases such as cancer, cardiovascular diseases, and neurodegenerative diseases, with a particular link to PD via the recessive gene products PINK1 and parkin." (PMID 34688664, 2021). "For PINK1, reduced expression was seen in all stages of cancer." (PMID 33322704, 2020). "Both the Oncomine and TIMER databases showed low expression levels of PINK1 in most cancer types." (PMID 33244455, 2020). "This concept prompted us to elucidate the immunological role of the mitophagy-related protein PINK1 across cancers to determine whether the immune system plays any role in the prognostic value of PINK1." (PMID 33244455, 2020). "Taken together, the results above reflect that PINK1 expression might affect cancer patient survival by influencing immune infiltration in the tumor microenvironment." (PMID 33244455, 2020). "These discrepancies in PINK1 expression in different kinds of cancer might be due to the heterogeneity of data collection as well as a result of the presence of specific biological properties in each cancer type." (PMID 33244455, 2020).
cancer (continued). "On the other hand, however, cell cycle changes induced by the PINK1 deletion may result in chromosomal aberrations and lead to the development of cancer depending on the type of the cells." (PMID 33066407, 2020). "Similarly, enhanced sensitivity of multidrug-resistant cancer cells to betulinic acid analog B5G1 that was induced by the inhibition of PINK1-Parkin dependent mitophagy resulted in liver cancer cell death." (PMID 32587855, 2020). "Common genetic mechanisms, especially those underlying cell cycle turnover and protein regulation such as those involving SNCA, PARK2, PARK8, ATM, PTEN, PINK1, and MC1R have been implicated in both neurodegeneration and cancer and perhaps explain this association." (PMID 32547471, 2020). "In addition to the role of ubiquitin-dependent receptors in mitophagy, PINK1 also plays an extensive role in cancer." (PMID 33244455, 2020). "Although the etiologies of PD and cancer are multifactorial, some factors associated with PD, such as α-synuclein aggregation; mutations of PINK1, PARKIN, and DJ-1; mitochondrial dysfunction; and oxidative stress can also be involved in cancer proliferation or cancer suppression." (PMID 33066407, 2020). "In summary, the inhibition of mitochondrial biogenesis by HIF depends mainly on the regulation of key genes, such as c-Myc, PGC-1, and PINK1, which may also provide new therapeutic targets for future cancer treatment." (PMID 32928258, 2020). "Taken together, our results revealed that the role of PINK1 might be context dependent and could vary among different cancers." (PMID 33244455, 2020). "Interestingly, PINK1 had a significant overall effect on cancers (OS: total number = 9,500, HR = 0.69, log-rank P = 0; DFS: total number = 9,500, HR = 0.82, log-rank P = 1.4e-07)." (PMID 33244455, 2020). "Above all, these findings could provide a view on the utility of the mitophagy-related protein PINK1 as a prognostic factor across cancers." (PMID 33244455, 2020). "O’Flanagan and O’Neill reviewed the function of PINK1 in cancer cell biology, with an emphasis on the mechanisms by which PINK1 interacts with PI3-kinase/Akt signaling, mitochondrial homeostasis, and the potential context dependent pro- and anti-tumorigenic functions of PINK1." (PMID 33615312, 2020). "The findings from this study indicated that PINK1 influenced the prognosis of patients with cancers and might probably via its interaction with infiltrating immune cells." (PMID 33244455, 2020). "Collectively, PINK1 acts as a tumor suppressor in most cancer types." (PMID 33244455, 2020). "PINK1 might work as a new biomarker for prognostic prediction and immune cell infiltration across cancers in the future." (PMID 33244455, 2020). "We confirmed that knockdown of PINK1 increased tumor sphere formation, suggesting that HEY1 may confer cancer cell stemness properties through PINK1." (PMID 31819034, 2019). "Alterations in BNIP3 or PINK1 transcript levels are found in cachectic muscle of cancer patients as well as in mouse models, but whether and how they regulate mitophagy-induced cachexia remains to be further studied." (PMID 31121959, 2019). "Given its key functions in mitophagy, PINK1 is a possible target for the treatment of cancer." (PMID 30344951, 2018). "PINK1 plays a dual role in tumorogenesis, it can both stimulate and inhibit cancer." (PMID 30344951, 2018). "We can therefore suggest that the interplay among PINK1/PARKIN/DJ-1 network during mitochondrial quality control in cancer biology may occur at the transcriptional level." (PMID 30274236, 2018). "Moreover, PINK1, which is associated with PTEN, is significantly involved in the development of cancer." (PMID 30344951, 2018). "Interestingly though, it was found that ARIH1 substitutes Parkin in the PINK1/Parkin-mediated mitophagy that takes place specifically in cancer cells." (PMID 30250843, 2018).
cancer (continued). "We suggest that the interplay among PINK1/PARKIN/DJ-1 network during mitochondrial quality control in cancer biology may occur at the transcriptional level." (PMID 30274236, 2018). "Finally, the role of the PINK1/Parkin pathway in cancer onset and progression has already been extensively reviewed." (PMID 30250843, 2018). "Mechanistically, the duality of PINK1 function in cancer cell biology may stem from its regulation of mitophagy, which may be tumor promoting in some circumstances and tumor suppressive in others, depending on the cellular context." (PMID 30595797, 2018). "These transcription factors related to the cell cycle suggests that the interaction among PINK1/PARKIN/DJ-1 network during mitochondrial quality control in cancer biology may be regulated at the transcriptional level." (PMID 30274236, 2018). "Taken together, our findings reveal the molecular mechanism that ART induces cytoprotective mitophagy through the PINK1-dependent pathway, suggesting that mitophagy inhibition could enhance the anti-cancer activity of ART." (PMID 30196190, 2018). "PINK1 was initially identified in cancer cells as a PTEN-induced protein kinase." (PMID 30595797, 2018). "The difference between BUB1B and PTEN-induced putative kinase 1 (PINK1) expression has been described previously to be associated with survival in adult but not in pediatric carcinomas." (PMID 29520253, 2018). "PINK1 has important pro-survival, anti-apoptotic, and cytoprotective functions, suggesting that it may be a promising target for cancer therapies." (PMID 28060722, 2017). "While the putative different roles that mitochondrial HSP90 chaperones and mitoUPR play in cancer and neurodegeneration remain unclear, it is interesting to note also PINK1 and Parkin have been suggested to play roles in both diseases." (PMID 29290944, 2017). "PINK1 may therefore be a direct target to block the cell cycle in cancer or for combination therapies to ‘prime’ cancer cells for treatment with other mitosis-targeting drugs." (PMID 26973853, 2016). "Our findings show for the first time that regulation of mitochondrial fission to fusion transitions by PINK1 is critical for cell cycle progression at G2/M and G0/G1 checkpoints necessary for cell division, growth and stress resistance, in particular in cancer biology." (PMID 26973853, 2016). "Based on the results of differential gene expression analysis of metastatic cancer cells, we previously showed that the expression levels of PINK1 were much higher in cancer cell lines with higher metastatic potential than in cancer cell lines with lower metastatic potential." (PMID 26555609, 2015). "Expression of PINK1 mRNA and protein ranges from high to low in different types of cancers, indicating the dual, context dependent pro and anti-tumorigenic role of PINK1 in cancer biology." (PMID 26504519, 2015). "Furthermore, PINK1 was originally found to be regulated by the tumour suppressor PTEN that regulates major signal transduction pathways in cancer and metabolism." (PMID 25345844, 2015). "The present findings regarding the functional link between NRF2 and PINK1, therefore, may also be relevant to cancer progression." (PMID 26555609, 2015). "Insect PINK1 could also be deployed to attempt to identify PINK1 inhibitors for the treatment of cancer, although further work would be needed to ascertain whether an inhibitor of insect PINK1 would also effectively suppress mammalian PINK1." (PMID 22645651, 2011). "Collectively, the distinct mitophagy mechanisms are differentially engaged in NDDs and cancers, with PINK1/Parkin signaling appearing to be more central to neurodegeneration, and receptor-mediated mitophagy pathways appearing to play a more prominent role in cancer." (PMID 40750884, 2025).